TNF (tumor necrosis factor)
Diseases named in the same sentence as TNF in open-access papers (continued):
Sharing a sentence is not in itself a finding about the gene and the disease.
atopic dermatitis (continued). "Therefore, the purpose of this study is to investigate whether PLG is effective in treating AD in DNCB-induced atopic dermatitis-like animal models and TNF-α/IFN-γ-stimulated HaCaT cell models." (PMID 35676724, 2022). "Therefore, we examined the role of neferine in TNF-α/IFN-γ-treated HaCaT cells to investigate whether neferine is a promising agent for the treatment of atopic dermatitis." (PMID 34361003, 2021). "Based on our findings it may be inferred that dogs with atopic dermatitis manifest skin lesions along with the inflammatory response, and the skin barrier proteins (Filaggrin and Involucrin) and inflammatory cytokines (TNF-α, IL-31, IL-13) seem to be key players in the pathogenesis of AD in dogs." (PMID 34075152, 2021). "Furthermore, we examined the mRNA expression of IL-6 in TNF-α/IFN-γ-induced HaCaT cells to evaluate whether SHCGT dose-dependently affects the atopic dermatitis." (PMID 34616298, 2021). "This aligns with previous studies demonstrating that IL-37b can inhibit the in vitro induction of pro-inflammatory cytokines (IL-6 and TNF-α) and chemokines (CXCL8, CCL2, and CCL5) related to atopic dermatitis." (PMID 40444012, 2025). "In atopic dermatitis models, ligustilide up-regulates filaggrin and SPTLC1, and reduces tumor necrosis factor-α (TNF-α), interferon-γ, and interleukin-6 (IL-6) to reinforce skin barrier function." (PMID 40904624, 2025). "Furthermore, in a model of 2,4-dinitrochlorobenzene (DNCB)-induced atopic dermatitis in mice, topical application of verbascoside reduced scratching and skin lesion severity, lowered IgE and IL-4 and IL-13 levels, and decreased inflammatory cytokines (TNF-α, IL-6, IL-4) in affected skin." (PMID 40724000, 2025). "The results showed that CSSH reduced pro-inflammatory cytokines (IL-1β, IL-6, IL-8, MCP-1 and CXCL10) and atopic dermatitis-related cytokines (IL-4, CCL17, MDC and RANTES) in TNF-α/IFN-γ-induced HaCaT cells." (PMID 38931136, 2024). "The results indicate a significant decrease in MAIT cells and CD69 subsets in atopic dermatitis, coupled with elevated CD38 and polyfunctional MAIT cells producing TNFα and Granzyme B (TNFα+/GzB+)." (PMID 38542456, 2024). "Multiple studies have demonstrated that the development of atopic dermatitis (AD) in mice involves multiple signaling pathways, including TLR, NF-κB, JAK-STAT, TNF, MAPK, and others." (PMID 39684557, 2024). "TNF-α has been reported to promote the production of CCL17 and CCL22 in keratinocytes, inducing features similar to atopic dermatitis." (PMID 38533495, 2024). "TNF-α/IFN-γ, which is extensively employed in atopic dermatitis simulations, acts on HaCaT cells and induces them to release chemokines and cytokines, such as IL-6, IL-8, CCL17, and CCL22." (PMID 37110740, 2023). "Our date showed that VAE inhibited CCL17 and CCL22 levels in TNF-α/IFN-γ-stimulated HaCaT keratinocytes and DNCB-induced atopic dermatitis animal models." (PMID 36793948, 2023). "In previous studies on marine organisms against atopic dermatitis, some studies reported that the red algae—Pyropia yezoensis-extract inhibited the production of pro-inflammatory chemokines induced by IFN-γ and TNF-α in HaCaT cells by down-regulating NF-κB." (PMID 37623728, 2023). "Notably, “atopic dermatitis”, “cardiovascular disease”, “clinical features”, and “TNF-α” were found to have a high betweenness centrality in the keyword co-occurrence mapping, which may represent intersections between disciplines and promote the generation of new research directions." (PMID 36837593, 2023). "In this study, we aimed to evaluate inhibitory effects of DHG water extract on atopic dermatitis in DNCB-induced NC/Nga mice and tumor necrosis factor (TNF)-α/interferon (IFN)-γ-treated keratinocytes." (PMID 35694270, 2022). "The anti-inflammatory activity of apamin was also investigated on TNF-α and IFN-γ-induced inflammatory responses in human keratinocytes in case of atopic dermatitis." (PMID 35456584, 2022).
atopic dermatitis (continued). "An evaluation of gut microbiota and innate immune responses in IgE-associated eczema showed that Ruminococcaceae in fecal samples was lower in atopic eczema infants than that in healthy controls and was negatively related to TLR2-induced IL-6 and TNF-α." (PMID 34335634, 2021). "We elucidated the anti-inflammatory effects of EAA on tumor necrosis factor-α/interferon-γ (TNF-α/IFN-γ)-treated human keratinocyte cells and 2,4-dinitrochlorobenzene (DNCB)-induced atopic dermatitis (AD)-like mice." (PMID 34500860, 2021). "The inflammatory factors TNF-α and IFN-γ in the skin of a patient with atopic dermatitis can activate the patient’s keratinocytes to produce an overexpression of inflammatory factors." (PMID 34361003, 2021). "The principal finding of the present study is that RJ regulates the inhibition of MAPKs and NF-κB activation in TNF-α induced HaCaT cells and attenuates the development of DNCB-induced atopic dermatitis lesions in Balb/c mice." (PMID 30866501, 2019). "Previous studies found that the expression of TNF-α and IFN-γ can induce the expression of IL-33 to promote allergic dermatitis." (PMID 28751921, 2017). "Therefore, the objective of this work was to investigate the anti-inflammatory effects of CPKEs on TNF-α activation in a HaCaT cell model and in a DNCB (1-chloro-2, 4-dinitrochlorobenzene)-induced atopic dermatitis animal model." (PMID 40004009, 2025). "TGF-β1 can inhibit the production of CCL-17 in human epidermal cells induced by TNF-α, suggesting that TGF-β1 may have a certain effect on the treatment of atopic dermatitis." (PMID 35069596, 2021). "Based on the current results, we suggest that Ac2-26 can not only alleviate the response of atopic dermatitis by regulating chemokines, but also suppress the activation of MAPK, NF-κB, as well as STAT/JAK signaling pathways in TNF-α/IFN-γ stimulated HaCaT cells." (PMID 33114438, 2020). "Our previous report demonstrated that Morus alba L. inhibited the TARC/CCL17 release in tumor necrosis factor-α (TNF-α) and interferon-γ (IFN-γ)-stimulated HaCaT keratinocytes, and suppressed the development of atopic dermatitis-like lesions induced by the house dust mite in NC/Nga mice." (PMID 30642008, 2019). "TNFα also contributes to the severity of atopic dermatitis, though TNF blockade by anti-TNF biologicals has thus far failed to improve outcomes in these patients." (PMID 30718654, 2019). "Recently, Kim demonstrated the effects of Costaria costata extract on atopic dermatitis via suppressing expression of TARC, eotaxin, TNF-α, and IL-6 in TNF-α and IFN-γ-stimulated HaCaT keratinocytes as well as release histamine in PMA and A23187-stimulated MC/9 mast cells." (PMID 30642008, 2019). "Therefore, we used TNF-α and IFN-γ as activators of atopic dermatitis-like response in HaCaT keratinocytes." (PMID 30642008, 2019). "We recently reported these cells to have different responses in atopic dermatitis cases than the MAIT cells, where Vα7.2+/CD161− T cells were showing a classical Th2/22 response and MAIT cells were showing upregulation in polyfunctional TNFα/GzB-producing cells." (PMID 38892082, 2024). "It is important to highlight that classical inflammatory markers such as TNF-α, IL-6, etc., may not consistently serve as indicators for atopic dermatitis induced by DNCB." (PMID 38834629, 2024). "For example, several studies using an atopic dermatitis mouse model showed that oral supplementation with Lactobacillus increased general skin barrier function, including decrease in severity of disease, subsequent TEWL, and tumor necrosis factor alpha (TNF-α) release." (PMID 36361857, 2022). "A recent study has shown that, in animal models of atopic dermatitis, atopic dermatitis-like symptoms were further improved by inhibiting HMGB1 expression in mast cells, preventing NF-κB nuclear translocation, and reducing the release of cytokines such as TNF-α and IL-1β." (PMID 34007295, 2021).
atopic dermatitis (continued). "This suggests that G-1, which reduces but does not completely prevent TNFα production and signaling, may be efficacious in limiting the severity of S. aureus skin infection in highly susceptible AD-HIES and atopic dermatitis patients." (PMID 30718654, 2019). "However, the application of ADSC-Exos has been proven to ameliorate atopic dermatitis-like symptoms via regulating inflammatory responses and reducing the expression of inflammatory cytokines, such as IL-4, IL-23, IL31, and tumor necrosis factor-α (TNF-α), in a mouse model." (PMID 31391108, 2019). "However, it is crucial to emphasize that no significant changes were observed in classic factors of atopic dermatitis, such as TSLP and pro-inflammatory cytokines (TNF-α, COX-2, IL-6, IL-31, etc.), in our study." (PMID 38834629, 2024).
chronic obstructive pulmonary disease (198 papers, 2006 to 2026). A chronic and progressive lung disorder characterized by the loss of elasticity of the bronchial tree and the air sacs, destruction of the air sacs wall, thickening of the bronchial wall, and mucous accumulation in the bronchial tree. "Although we found that the TNF signaling associated with the development of this disease in chronic obstructive pulmonary disease model mice, our findings need to be fully verified by future in vivo experiments." (PMID 40343927, 2025). "Pro-inflammatory mediators such as cytokines (IL-1, IL-6, TNF, etc.), ROS, and proteolytic enzymes are implicated in cell and tissue damages associated with many chronic inflammatory diseases, including chronic obstructive pulmonary disease (COPD)." (PMID 38675465, 2024). "Dysbiosis can lead to chronic inflammation, with elevated levels of pro-inflammatory cytokines, such as IL-6, TNF-α, and IL-1β, being linked to an increased risk of cardiac arrhythmias." (PMID 38892965, 2024). "Elevated circulating levels of TNFα and IL-1b mediate the higher susceptibility to cardiac arrhythmia in type 2 diabetic rats." (PMID 34623540, 2023). "High-fructose diets cause heart–gut axis disorders that promote cardiac arrhythmia through potentiating proinflammatory mediator, such as tumor necrosis factor alpha (TNF-α), nuclear factor-κB (NF-κB), and interleukin 6 (IL-6)." (PMID 37367916, 2023). "Our group has recently reported that elevated circulating levels of TNFα and IL-1b are responsible for higher susceptibility to cardiac arrhythmia in type 2 diabetic rats." (PMID 34623540, 2023). "For other targets, TNF shows statistically significant evidence of association with the susceptibility of chronic obstructive pulmonary disease such as chronic bronchitis." (PMID 23533462, 2013). "Furthermore, serum TRAIL levels are associated with TNF-α and decreased lung function in patients with chronic obstructive pulmonary disease." (PMID 36193083, 2022). "The tumor necrosis factor alpha (TNF-α) polymorphism may play an important role in chronic obstructive pulmonary disease (COPD) susceptibility." (PMID 35126452, 2021). "This is also the case in individuals with cancer cachexia, chronic obstructive pulmonary disease (COPD), and disuse who show elevated serum TNF-α levels which correlate with muscle loss." (PMID 32751276, 2020). "Chronic obstructive pulmonary disease (COPD) is characterized by increased production of proinflammatory cytokines, particularly TNF-α, which is associated with disease severity and loss of bone mass." (PMID 29058226, 2017). "Chronic obstructive pulmonary disease (COPD) is characterized by reduced lung function associated with increased local and systemic inflammatory markers, such as TNFα and IL-1β." (PMID 27883019, 2016). "In this context, the rs1800610 polymorphism in the TNF-α gene has been associated with several chronic diseases, including cancer, and the development of chronic obstructive pulmonary disease (COPD), as well as other infectious disease like hepatitis B virus (HBV) infection." (PMID 40881695, 2025). "Of the five patients with chronic obstructive pulmonary disease, one received anti-TNF-α therapy, and four received anti-IL-23." (PMID 40699767, 2025). "Some studies suggest that specific biologics, such as TNF inhibitors, may worsen pulmonary diseases in high-risk patients, mainly those with chronic obstructive pulmonary disease (COPD) and interstitial lung disease (ILD)." (PMID 40648921, 2025). "Measuring 30 cytokines in 936 sputum samples from patients with chronic obstructive pulmonary disease, we observed significant increases (IL-17A, TNF-α, IL-1β, IL-10) between stable and exacerbation states." (PMID 38836471, 2024). "A significant positive correlation was found between serum TNF-α and VitD levels, which was also noticed in a study on patients with chronic obstructive pulmonary disease." (PMID 39062153, 2024).
chronic obstructive pulmonary disease (continued). "Several researches had shown that miR-155HG regulated the expression of TNF-α, IL-1β, IL-10, and IL-12, together with GM-CSF-mediated polarization of M1/M2 macrophages in the progression of chronic obstructive pulmonary disease (COPD)." (PMID 35434143, 2022). "The authors’ previous study found that compared with healthy individuals, patients with the chronic obstructive pulmonary disease have elevated levels of serum Activin A correlated with TNF-α expression." (PMID 36375297, 2022). "The activation of the TNF-alpha system has been put forth clearly in chronic obstructive lung disease characterized by chronic hypoxemia; however, the impact of hypoxemic conditions on cytokine generation in OSAS is less known." (PMID 32454912, 2020). "As we know, TNF-α is an important inflammatory cytokine in the development of lung inflammation and higher levels of TNF-α are associated with chronic obstructive pulmonary disease." (PMID 31417879, 2019). "TNF-α and IL-32 are also critical mediators in some inflammatory diseases, including RA, chronic obstructive pulmonary disease, and graft-vs.-host disease." (PMID 29545920, 2018). "Potato extract has been shown to increase the expression of IL-10 and reduce the expression of TNF-α in serum and lung tissues of rats with cigarette smoke-induced chronic obstructive pulmonary disease." (PMID 29495317, 2018). "In addition, older age and specific comorbidities that are relatively prevalent in the RA population, such as diabetes mellitus or chronic obstructive pulmonary disease (COPD), have been associated with an increased risk of SIEs during anti-TNF therapy." (PMID 29246162, 2017). "In addition, an association between TNF-α and objective measures of depression and fatigue is shown in studies of chronic obstructive pulmonary disease (COPD)." (PMID 26925234, 2016). "Even more, there is evidence of a substantial involvement of the tumor necrosis factor-alpha system in the pathophysiology of cardiac arrhythmia, while the role of Interleukin 6 remains inconclusive." (PMID 24770373, 2014). "Fall lung airway resistance, rise in dynamic lung compliance, decreased serum levels of IL-8, GM-CSF, TNF-α, and ET-1 in rat model of stable phase chronic obstructive pulmonary disease induced by cigarette smoke exposure were also observed." (PMID 21512444, 2011). "TNF-α mediated inflammation is thought to play a key role in the respiratory and systemic features of Chronic Obstructive Pulmonary Disease." (PMID 21985478, 2011). "It has also been reported that Sangju Qingjie Decoction can treat chronic obstructive pulmonary disease rats by increasing the abundance and diversity of pulmonary microbiota and reducing inflammatory factors, such as IL-6, IL-8, and tumor necrosis factor (TNF)-α." (PMID 39472001, 2024). "This is specifically true for tumor necrosis factor-α (TNF-α), interleukin-1 (IL-1), and IL-6, all of which may induce cardiac arrhythmias." (PMID 36851603, 2023). "Moreover, several proinflammatory cytokines, such as TNF-α, IL-1β, and IL-17, have been shown to induce cardiac arrhythmias in various animal models." (PMID 37845390, 2023). "Moreover, it has been recently demonstrated the role of both TNFα and IL-1b in the initiation and maintenance of cardiac arrhythmias in humans." (PMID 34202017, 2021). "In addition, LHQW significantly decreased the release of inflammatory mediators such as IL-8, TNF-α, IL-17, and IL-23 in the sputum and IL-8 and IL-17 in the blood in patients with acute exacerbation of chronic obstructive pulmonary disease." (PMID 33071781, 2020). "For example, a study using a mouse model of chronic obstructive pulmonary disease found that memantine could inhibit the expression of IL-6, TNF-α, and interferon-γ, thereby reducing pulmonary inflammation." (PMID 33174867, 2020).